YBX1 (Y-box binding protein 1)
Diseases named in the same sentence as YBX1 in open-access papers (continued):
Sharing a sentence is not in itself a finding about the gene and the disease.
liver cancer (28 papers, 2009 to 2025). An epithelial or non-epithelial malignant neoplasm that arises from the liver. "Our previous study demonstrates that overexpression of YBX1 suppresses cell growth in some of the liver cancer cells, supporting that the effects of YBX1 on cell proliferation are complicated." (PMID 40812419, 2025). "To confirm the regulation of PD‐L1 and CD47 by YBX1 in human liver cancer cells, we knocked down YBX1 in HepG2 cells and LM3 cells, respectively." (PMID 38981064, 2024). "In a separate study focusing on liver cancer, researchers observed that reducing YBX1 expression significantly decreased cell proliferation in MHCC97H and HCCLM3 cells, while overexpressing YBX1 in BEL7402 and SMMC7721 cells inhibited cell growth." (PMID 38255791, 2024). "The lncRNA HULC (highly up-regulated in liver cancer) has also been shown to drive ERK-mediated YBX1 phosphorylation, thereby increasing the transcription of oncogenic genes in HULC-expressing cells." (PMID 34266873, 2021). "YBX1 emerged as a potential binding partner with strongest and significant correlation to survival in liver cancer patients." (PMID 32587247, 2020). "Accordingly, we find high YBX1 expression correlated with poor overall survival in liver cancer, as well." (PMID 32587247, 2020). "LincNMR and YBX1 mRNA expression significantly correlate in liver cancer patient samples as well as with RRM2, TK1, and TYMS mRNA expression." (PMID 32587247, 2020). "Knockdown of lincNMR significantly decreased the YBX1 activity in two independent liver cancer cell lines." (PMID 32587247, 2020). "For example, the long noncoding RNA highly upregulated in liver cancer (HULC) can specifically bind to the Y-box binding protein 1 (YB-1) promoter, thus silencing the mRNA of this gene." (PMID 32042268, 2020). "Indeed, RRM2 and TK1 were decreased by YBX1 inactivation, which is involved in nucleotide metabolism in liver cancer cells." (PMID 40812419, 2025). "In addition to the significant roles of lncRNA and miRNA in the development and progression of liver cancer, the circular RNA cFAM210A, degraded by the HBx, plays a protective role against liver cancer by inhibiting YBX1-mediated trans-activation." (PMID 38188582, 2023). "Our findings also suggest that USP2-AS1 could increase the protein level of HIF1α by enhancing YBX1 protein binding to HIF1α mRNA under hypoxia and the therapeutic effect of lenvatinib can be enhanced by combination with HIF1α inhibitors in liver cancer." (PMID 35692750, 2022). "To identify how and whether the interaction between NEAT1 and YB1 contributed to liver cancer, we overexpressed YBX1 in NEAT1-KD HepG2 cell lines." (PMID 34769497, 2021). "Together, these data show that lincNMR interacts with and regulates YBX1, YBX1 mimics the impact of lincNMR on cell proliferation, and the regulation of lincNMR by YBX1 generates a feedforward loop leading to the correlation of expression in liver cancer." (PMID 32587247, 2020). "In liver cancer, YBX1 interacts with CBX8 to regulate the cell cycle and promote the proliferation of liver cancer cells." (PMID 40799245, 2025). "By enhancing liquid-liquid phase separation of YBX1, circASH2 accelerates the decay of TPM4 transcript, impeding liver cancer metastasis." (PMID 40799245, 2025). "Assays such as RAP-MS have revealed the role of lincNMR and its interaction with YBX1 and RRM2, leading to liver cancer." (PMID 40861865, 2025). "In summary, their regulation, their association with survival, and their correlation of expression links lincNMR, YBX1, RRM2, TK1, and TYMS to liver cancer and to each other, respectively." (PMID 32587247, 2020). "Knockdown of lincNMR, YBX1, TK1, and TYMS also significantly inhibited the colony-formation capacity of liver cancer cells." (PMID 32587247, 2020).
liver cancer (continued). "CircASH2 enhances the liquid-liquid phase separation of nuclear Y box binding protein 1 (YBX1), thus promoting the decay of TPM4 transcripts, highlighting the role of tumor suppressor circRNAs and their intricate regulatory mechanisms in liver cancer progression." (PMID 40224186, 2025). "Although reducing YBX1 expression severely decreases cell proliferation among different cancer types, while hyperactivation of YBX1 also inhibited cell proliferation in MCF-10A as well as in liver cancer cells." (PMID 40812419, 2025). "Likewise, DDX17 functions as a transcriptional regulator, driving the binding of the nuclear Y-box binding protein 1 (YB1) to the epidermal growth factor receptor (EGFR) gene and promoting its transcription, ultimately facilitating liver cancer metastasis." (PMID 38732173, 2024). "For example, YBX1 is not expressed or maintained at very low levels in normal adult liver, but its expression increases again during fetal development or liver injury repair, as well as in liver cancer." (PMID 39497723, 2024).
nasopharyngeal carcinoma (26 papers, 2010 to 2026). A carcinoma arising from the nasopharyngeal epithelium. "Elevated YBX1 expression is linked to poorer prognosis in nasopharyngeal carcinoma (NPC), suggesting its potential as a prognostic biomarker for NPC patients, aiding clinicians in treatment evaluation and strategy adjustment." (PMID 40799245, 2025). "For instance, lncRNA FOXD3-AS1 enhances YBX1 transcription via H3K27Ac modification, promoting nasopharyngeal carcinoma progression." (PMID 40799245, 2025). "LINC01133 binding to YBX1 partially reverses its inhibition on nasopharyngeal carcinoma cell proliferation, migration, and invasion." (PMID 40799245, 2025). "YBX1 expression has been shown to have clinicopathological significance to be a potential predictive marker of recurrence in nasopharyngeal cancer patients." (PMID 20428086, 2010). "Additionally, circIPO7 facilitates YBX1 nuclear translocation and promotes nasopharyngeal carcinoma metastasis and cisplatin chemotherapy resistance by promoting its serine 102 phosphorylation via AKT kinase." (PMID 40799245, 2025). "Similarly, circIPO7 binds to YBX1 and facilitates its nuclear translocation, which promotes nasopharyngeal carcinoma metastasis and cisplatin chemoresistance." (PMID 38378679, 2024). "YBX1 serves as an oncogene in many cancers, including nasopharyngeal cancer." (PMID 34395290, 2021). "In nasopharyngeal carcinoma, YBX1 promotes the expression of AURKA protein by directly binding to AURKA mRNA, thereby promoting the proliferation and invasiveness of nasopharyngeal carcinoma cells." (PMID 40799245, 2025). "In nasopharyngeal carcinoma (NPC), the expression of YBX1 positively correlates with Vimentin expression, and TGF-β1 stimulation promotes YBX1 expression and EMT within CNE1 cells." (PMID 40346063, 2025). "In nasopharyngeal carcinoma (NPC), RNA pull-down and RIP assays was used to validate the binding of YBX1 and LINC01133." (PMID 35747817, 2022).
cervical carcinoma (23 papers, 2020 to 2026). A carcinoma arising from either the exocervical squamous epithelium or the endocervical glandular epithelium. "LncRNA HITT can reduce HIF1α protein translation through YBX1 in colorectal tumors and cervical cancer while forming a feedback regulatory loop with HIF1α to regulate angiogenesis and tumor growth." (PMID 35692750, 2022). "In cervical cancer, NSUN2 promotes m5C modification on KRT13, and m5C-methylated KRT13 is recognized and stabilized by the m5C reader protein YBX1." (PMID 41462962, 2025). "In cervical cancer patients, NSUN2 and YBX1, which catalyze and recognize methylation sites, respectively, induce KRT13 mRNA methylation and translational activation." (PMID 37325635, 2023). "In contrast, NSUN2 played a robust role for tumorigenesis in cervical cancer via promoting m5C modification on KRT13 transcripts, which were then recognized and stabilized by an m5C reader protein YBX1." (PMID 35280737, 2022). "As it physically bound itself to Y-box binding protein 1 (YBX1), recruited YBX1 to the PIK3CA promoter, and it mediated the anti-cancer effects of baicalein in cervical cancer via activating PI3K/Akt pathway." (PMID 34680171, 2021). "In addition, LARP1 can positively regulate the mRNA expression of multiple components of the mTOR carcinogenic pathway and other anti-apoptotic [B-cell lymphoma 2 (BCL2)] and pro-migration [Y-box binding protein-1 (YB1)] proteins, leading to LARP1-mediated cervical cancer tumorigenesis." (PMID 37507746, 2023).
colon carcinoma (23 papers, 2008 to 2026). "In colon cancer, Y-box binding protein 1 (YB-1) contributes to oxaliplatin resistance, and this resistance depends on NONO." (PMID 38328550, 2024). "HEK293 cells and colon cancer HT29 cells that overexpressed the YBX1-S176A (serine to alanine) mutant showed a significant decrease in NF-κB activation ability compared to WT-YBX1-κB, confirming that Ser-176 phosphorylation activates NF-κB for YBX1-κB." (PMID 37465677, 2023). "YBX1 is phosphorylated at S165 and S176 in colon cancer, which promotes NF-κB activation and tumorigenic potential, however, the kinase responsible for these phosphorylation events was not conclusively identified." (PMID 32178290, 2020). "Several RBPs have been previously identified as mediators of exosome miRNA sorting in various model systems, including major vault protein in colon cancer cells, hnRNPA2B1 in T cells, and YBX1 in HEK293T cells." (PMID 32819370, 2020). "Our lab first discovered that the phosphorylation of specific sites on YBX1 is critical for colon cancer progression, including S165 and S176." (PMID 33375283, 2020). "We also investigated YBX1 expression and its dependency on RAS signaling in KRAS-inducible transgenic colon cancer cell lines and mice, to provide a rationale for the observed sub-cellular localization of YBX1 in CRC tissue." (PMID 26779809, 2016). "We further carried out tissue microarray [TMA] analysis [US Biomax Inc., Rockville, MD] for YBX1 in specimens from both normal and different stages of colon cancer by using immunohistochemical [IHC] methods." (PMID 26318844, 2015). "We proved that mutation of S165 to “A” greatly reduced the NF-κB activating ability of YBX1, and therefore, greatly reduced cell growth and colony formation in colon cancer HT29 cells." (PMID 26318844, 2015). "Overall, this data strongly suggested that YBX1 potentially plays a very important role in colon cancer development, and possibly in the transition between polyps and cancerous cells as well." (PMID 26318844, 2015). "Compared with normal specimens, a marked increase of YBX1 expression was observed in progressive stages of colon cancer." (PMID 26318844, 2015). "Oncomine data also indicated that out of the 37 colon cancer patient specimens, the majority showed increased expression of YBX1." (PMID 26318844, 2015). "Over-expression of YBX1 in breast, prostate and colon cancer confirmed its role as a positive modulator of proliferation." (PMID 21170361, 2010). "Furthermore, multiple studies have reported on the strong regulation between YBX1 and NF-κB in colon cancer." (PMID 37465677, 2023). "Recently, our lab has discovered YBX1 as a novel NF-κB activator in colon cancer, where overexpression of YBX1 could promote cancerous phenotype." (PMID 33375283, 2020). "Overexpression of the S165A-YBX1 mutant in either HEK293 cells or colon cancer HT29 cells showed dramatically reduced NF-κB activating ability as compared with that of WT-YBX1, confirming that S165 phosphorylation is critical for the activation of NF-κB by YBX1." (PMID 26318844, 2015). "Furthermore, although our study is mainly focused on colon cancer, it is highly possible that phosphorylation of S165 of YBX1 also plays an important role in other types of cancer as well." (PMID 26318844, 2015). "Importantly, GeneNote data, Oncomine data, together with our tissue microarray data strongly support the overexpression of YBX1 in cancer, particularly, in colon cancer." (PMID 26318844, 2015). "Our tissue microarray data suggested that YBX1 is overexpressed not only in different stages of colon cancer specimens but also in polyps, indicating a potential role YBX1 may play in early stage of colon cancer development." (PMID 26318844, 2015). "We found that YBX1 expression is correlated with a bad clinical outcome in colon cancer patients." (PMID 21170361, 2010). "Additionally, phosphorylation of YBX1 can activate the NF-κB pathway in colon cancer." (PMID 41507134, 2026).
colon carcinoma (continued). "Additionally, it is noteworthy that the phosphorylation of YBX1 at other specific sites such as S176 and S165 and R205 methylation play a crucial role in activating NF-κB which is involved in driving cell proliferation in colon cancer." (PMID 38255791, 2024). "A recent study on the role of Ybx1 phosphorylation in colon cancer has shown that S176 phosphorylation is responsible for an aggressive form of colon cancer, and its inhibition could be an important treatment option for colon cancer." (PMID 29068423, 2017). "With our analysis, we were not able to define a significant prognostic impact for YBX1 staining in primary colon cancer." (PMID 26779809, 2016).
non-small cell lung carcinoma (18 papers, 2011 to 2026). A group of at least three distinct histological types of lung cancer, including non-small cell squamous cell carcinoma, adenocarcinoma, and large cell carcinoma. "CDH1 downregulation in non-small cell lung cancer promotes EGFR transcription by activating YBX1 phosphorylation." (PMID 40799245, 2025). "RNA-m5C methylation mediated by NSUN2/YBX1/QSOX1 confers resistance to treatment in non-small cell lung cancer." (PMID 40799245, 2025). "HOXC-AS3 lncRNA binds to YBX1, inhibiting MDM2-mediated YBX1 ubiquitination, and promoting non-small cell lung cancer growth and metastasis." (PMID 40799245, 2025). "YBX1 promoted autophagy and decreased drug sensitivity of human non-small cell lung cancer cells by targeting p110β/Vps34/BECN1 pathway." (PMID 36642732, 2023). "It was previously reported that YBX1 is phosphorylated and activates Akt signal transduction in non-small-cell lung cancer cells." (PMID 34202873, 2021). "However, the relationship between YBX1 and autophagy in non-small cell lung cancer (NSCLC) remains unclear." (PMID 32561752, 2020). "MELTF-AS1 directly binds and drives the phase separation of the RNA-binding protein YBX1, which is involved in tumorigenesis, thereby activating ANXA8 transcription and promoting non-small cell lung cancer development." (PMID 40799245, 2025). "In non-small cell lung cancer (NSCLC), aberrant m5C hypermethylation mediates the resistance to gefitinib via the NSUN2/YBX1/QSOX1 axis." (PMID 38654314, 2024). "LncRNA RMRP recruits YBX1 to upregulate the transcription of TGFBR1, thereby promoting the proliferation and progression of non-small cell lung cancer." (PMID 38491348, 2024). "RMRP is upregulated in non-small cell lung cancer (NSCLC) and promotes proliferation, invasion, and migration by interacting and recruiting YBX1 to the TGF-β receptor 1 (TGFBR1) promoter, upregulating TGFBR1 and enhancing the TGFBR1/SMAD2/SMAD3 growth signaling pathway." (PMID 36754845, 2023).
triple-negative breast carcinoma (17 papers, 2007 to 2026). An invasive breast carcinoma which is negative for expression of estrogen receptor (ER), progesterone receptor (PR), and human epidermal growth factor receptor 2 (HER2). "For instance, in triple-negative breast cancer cells, YBX1 has been shown to directly activate the transcription of CTPS1 by binding to its promoter region." (PMID 40819060, 2025). "Through protein kinase B/mammalian target of rapamycin/vascular endothelial growth factor signaling, HUMT exerted its function of proliferation and metastasis by recruiting Y-box binding protein 1 protein in triple-negative breast cancer." (PMID 35293286, 2022). "In triple-negative breast cancer, YBX1 is also closely related to glycolytic genes." (PMID 41507134, 2026). "YBX1/CTPS1 is an important axis in the progression of triple-negative breast cancer." (PMID 34991621, 2022). "Taken together, YBX1 could directly activate CTPS1 transcription by binding to its promoter region in triple-negative breast cancer." (PMID 34991621, 2022). "In triple-negative breast cancer (TNBC), knockdown of YBX1 inhibited the expression of glycolytic genes (ENO1, SLC2A6, LDHA, PFKP, PGAM1, and GPI) and downregulated the expression of EMT-related genes and tumor migration and invasion." (PMID 41507134, 2026). "LncRNA HUMT recruits YBX1 to form a new transcriptional complex and activates the expression of forkhead box k1 (FOXK1) in triple-negative breast cancer, thereby promoting lymphangiogenesis and metastasis." (PMID 40799245, 2025). "LncRNA HUMT recruits Y-box binding protein 1 (YBX1) to form a new transcription complex and activates the production of forkhead box k1 (FOXK1), hence increasing VEGF expression (VEGFC) in triple-negative breast cancer (TNBC)." (PMID 36471363, 2022). "In addition, the overexpression of piR-YBX1 can inhibit the binding of YBX1 to RAF1, a key molecule in the MAPK signaling pathway, and then inhibit p-MEK and p-ERK1/2, and inhibit the proliferation and metastasis of triple-negative breast cancer." (PMID 40799245, 2025).